SOX2 (SRY-box transcription factor 2)
Diseases named in the same sentence as SOX2 in open-access papers (continued):
Sharing a sentence is not in itself a finding about the gene and the disease.
tumor (continued). "Indeed, immunostaining revealed that the majority of tumor cells exhibit nuclear expression of HIF-1 α and HIF-2 α, along with SOX2 and OCT3/4." (PMID 28249000, 2017). "In our study, we demonstrated that ICG-001 could inhibit the growth of tumor spheres and reduce the expression of CD44 as well as other stem cell markers such as OCT-4, Sox2, Nanog, Survivin." (PMID 28893318, 2017). "Here we show that VEGFA induction of Sox2 promotes EMT and tumor metastasis." (PMID 28504716, 2017). "Furthermore, the stem cell-related genes Oct4, Sox2 and TERT were upregulated in cisplatin-resistant cells, and cisplatin resistant cells were able to generate more tumor spheres than vehicle cells during primary and secondary sphere assay." (PMID 27102300, 2016). "Tumor cells and iHepL cells do not contain transgenes for Oct4 or Sox2, pointing at Klf4 and Myc as probably responsible for induced tumorigenicity and excluding rare partially pluripotent cells as responsible for tumor formation." (PMID 27460218, 2016). "Importantly, the tumours recapitulated the histopathology and gene expression signatures of human GBM, including presence of necrosis, neovascularization, nestin and Sox2 expression and a strong enrichment in the Verhaak mesenchymal subtype gene signature." (PMID 27350048, 2016). "Further analysis basing on the different Lum subtypes revealed that FGFR1 correlated with the high pN (p = 0.023), pT stages (p = 0.003), large tumor size (p = 0.005), the presence of LVI (p = 0.010), p-cadherin (p = 0.028), SYN (p = 0.009) and SOX2 (p = 0.034) expression in Lum A subtype only." (PMID 26673008, 2016). "Pathways related with amino-acid metabolism were among the most deregulated, illustrating that SOX2 expression is critical for maintaining metabolic homeostasis in the GSC population, and plays important role in different tumor microenvironment conditions, such as hypoxic stress conditions." (PMID 27669421, 2016). "This may in part be explained by the inherent intra-tumor heterogenity within GBM tumors, with previous studies demonstrating spectral expression patterns for both SOX2 and pSTAT3 including GBM." (PMID 27617262, 2016). "Endoxifen-induced tumours expressed GFAP, nestin, Sox2, Olig2, PDGFRa and doublecortin (Fig. 5E1-J1), and were indistinguishable from tumours generated by Adeno-Cre or Adeno-GFAP-Cre injection and as shown in Fig. 5E2-J3." (PMID 26704996, 2016). "The distributions of HIF-2α+ cells and SOX2+ HIF-1α+ RNApII-S2P-/low cells overlapped only occasionally in the areas around large ischemic necroses, and the overall distribution patterns of these 2 subpopulations of tumor cells were essentially different." (PMID 26799577, 2016). "RT-PCR analyses of fresh frozen tumor tissue verified that tumors with a high expression of SOX2 had low or absent expression of CDX2." (PMID 27411517, 2016). "We reexamined the role of SOX2 in PDAC, because we had previously determined that inducible elevation of SOX2 in various types of tumor cells leads to growth inhibition rather than growth promotion." (PMID 27145457, 2016). "In this study we combined the tumor cell specific markers in a double immunofluorescence protocol with the following panel of stem cell markers: CD133, Nestin, Musashi-1, Sox-2 and Bmi-1, to characterize the phenotype of migrating glioma cells." (PMID 27171431, 2016). "A single cell from the primary tumor spheres could form secondary tumor spheres, and expressed stem cell makers: CD133, SOX2 or Nestin." (PMID 27557508, 2016). "Moreover, in addition to p85β (PIK3R2) and Sox2, IRS1, VEGF and CXCR4 have been reported to be target genes of miR-126-3p and to participate in miR-126-3p-induced tumor suppression." (PMID 27191494, 2016).
tumor (continued). "SOX2 mRNA expression levels were investigated in 15 tumor and 15 non-tumorous tissue samples, and a strong correlation, (r = 0.875, p = 0.001), was observed between the SOX2 copy numbers and the relative SOX2 mRNA expression level." (PMID 26780934, 2016). "Although inducible elevation of SOX2 leads to PDAC growth inhibition in vitro as well as a substantial reduction in tumor growth, this does not indicate that SOX2 plays little or no role in promoting the growth of PDAC." (PMID 27145457, 2016). "In our in vitro model expressing SOX2, we found that SOX2 did not increase the migratory effect of tumor cells and was not a major regulator of EMT." (PMID 27411517, 2016). "Because most SQCCs express high levels of SOX2 and low levels of SOX9 and show evidence of PI3K activity in at least some tumor cells (which could be stem cells), the mechanism we uncovered in stem cells may continue to promote squamous identity in SQCCs." (PMID 27880766, 2016). "SOX2 and NANOG were immunolocalized to the nuclei of tumor cells with high frequency." (PMID 26799577, 2016). "These experiments have revealed that the typical cell clusters derive from SOX2+ cells, but intriguingly, the bulk of the tumor mass does not." (PMID 26763580, 2016). "Findings from clinical specimens led us to assess whether SOX2 may regulate gene sets related to NED and tumor progression." (PMID 26540632, 2016). "Although this study provided support in vitro for a critical role of SOX2 in the stemness of PDAC, the effects of SOX2 on the tumorigenicity of PDAC tumor cells were not examined." (PMID 27145457, 2016). "As the tumor microenvironment can regulate stemness and therapeutic resistance of cancer cells, we determined that cancer cells with Crk-induced EMT did not possess enhanced levels of stem cell markers including Nanog, Sox2, Oct3/4, and CD44." (PMID 27027347, 2016). "We observed that SOX2 and livin expressions were significantly higher in tumor tissues compared with their adjacent non-neoplastic tissues." (PMID 28983346, 2015). "Consistent with in vitro data, FoxM1-expressing cells were highly enriched in Sox2 positive tumor cells compared to Sox2 negative/low tumor cells." (PMID 26444992, 2015). "To investigate the relevance of the described AKT/SOX2 molecular axis in vivo, we next performed xenotransplantation experiments of human BC cells that were micro-injected into the yolk sac of zebrafish embryos, and quantified tumor formation in dependence of AKT and SOX2." (PMID 26498353, 2015). "Cancer cell proliferation and capacity for transformation were impaired in the CD133 stable knockdown cell lines, which were accompanied by the suppression of stemness genes including NANOG, OCT4, SOX2, and c-MYC, suggesting that CD133 expression is required for tumor tissue growth and survival." (PMID 26539911, 2015). "The overexpression of OCT4, SOX2, and KLF4 can reprogram or dedifferentiate somatic cells into induced pluripotent stem cells, which resemble the de-differentiation process that cancer cells undergo during tumor formation." (PMID 26582602, 2015). "Expression of Class III β-tubulin, Sox2, and Survivin was not significantly correlated with age, histotype, grade, ascites, or residual tumor (p > 0.05)." (PMID 26198101, 2015). "Sox2 IHC of 5 NHL-CNS with adjacent brain revealed Sox2-immunopositive cells in every case, also primarily at the interface of the tumor with the adjacent non-neoplastic brain but also with occasional cells within the masses of the tumors." (PMID 25713758, 2015). "These oncospheres are characterized by SOX2, OCT4, NANOG and ALDHA1 mRNA expression, high colony formation efficiency, enhanced growth in soft agar and enhanced tumourigenic potential in vivo that recapitulates the parental tumour." (PMID 26270676, 2015).
tumor (continued). "Moreover, these GSC populations in vitro expressed high levels of “classical” stem cells markers (Nestin, Sox2 and CD133) and low levels of differentiation markers (βIII-tubulin and glial fibrillary acid protein) when compared to bulk tumor cells." (PMID 25955030, 2015). "In such cases, double-labeling with Sox2 and a tumor marker would be superfluous and was not performed." (PMID 25713758, 2015). "SOX2 and livin were over-expressed in tumor tissues as compared to the corresponding adjacent non-neoplastic tissues." (PMID 28983346, 2015). "Interestingly, we found that rapamycin inhibited mTOR signaling in addition to simultaneously downregulating the expression of CD44, SOX2 and MMP-2 and that it affected cell growth and tumor size and weight both in vitro and in vivo." (PMID 26202311, 2015). "Furthermore, we divided tumor samples into two groups on the basis of USP22 amounts and studied the differences of SOX2 expression." (PMID 24466336, 2014). "Stemness-associated genes Oct4 and SOX2 and putative stem cell markers, ALDH and Oct4 were expressed in the tumor sphere cells but not in the parental adherent monolayer HeLa cells." (PMID 24676900, 2014). "Immunohistochemistry of tumor tissue sections obtained from PANC-1 xenografts reveals that the single treatments reduced the expression of the ALDH1, CD44, Sox2, CxCR4 and Ki-67, and induced cleavage of Caspase-3, whereas both treatments together had strongest effects." (PMID 25015789, 2014). "There is not any differences in TUNEL and Ki67 positive cell rate in xenograft tissues formed by the Sox2-positive and negative SiHa and C33A cells, suggesting the decreased tumor growth by EGFP− cell was not due to the less cell viability." (PMID 24489842, 2014). "The cohort included patients for whom the endocrine therapy was successful (responders) and the tumour had not returned over a period of 8 years (n = 33 patients) and in which Sox2 was weakly expressed in a low percentage of cells (Allred score ≤2)." (PMID 24178749, 2014). "In the positive cases, SOX2 expression was never seen in the whole tumor, but positive nuclei were found in limited parts." (PMID 25010701, 2014). "Representative photographs of tumour samples with negative, moderate and strong Sox2 staining are shown." (PMID 24178749, 2014). "Importantly, arsenic trioxide markedly reduced clonogenic capacity of the tumor neurospheres, and the stem-like CD133-positive fraction was also diminished along with expression of the stem cell markers SOX2 and CD133." (PMID 24685274, 2014). "In addition, we also detected the stem cell markers (OCT4, SOX2, and Nanog) expression and AKT/MAPK phosphorylation levels in these tumor tissues with different cell origin." (PMID 25369529, 2014). "The expression of SOX2 and SOX2OT was found to be significantly up-regulated in tumor xenografts." (PMID 25006803, 2014). "Compared with the Sox2-negative cells, the Sox2-positive SiHa and C33A cells exhibited greater capacities for self-renewal, differentiation and tumor formation." (PMID 24489842, 2014). "Noteworthy, these SOX2 positive metastasis were morphologically more alike the tumor compartments having SOX2 positive nuclei than the rest of the primary tumor (data not shown)." (PMID 25010701, 2014). "Western blotting demonstrated that there was little expression of Oct4 and SOX2 in the parental adherent monolayer HeLa cells, while their expression was evident in tumor sphere HeLa cells cultured under a nonadhesive culture system." (PMID 24676900, 2014). "In P22 cultures, 52 7% of cells were positive for SMA, while the GFAP (27 5%), beta-tubulin III (21 9%), and SOX2 (36 3%) positive cells are most likely human tumor cells as there was not a complete selection towards rat stromal cells." (PMID 24349039, 2013).
tumor (continued). "Our results clearly showed that AT13387 not only reduced the in vivo tumor formation, but also reduced the formation and growth of NPC tumor spheres accompanied by reduced expression of cancer stem-like cells markers CD44 and SOX2." (PMID 24156782, 2013). "Fourth and finally, the function of Sox2 to promote castration-resistant tumor growth appears to not be via re-activation of established hES pathways, but rather through a novel mechanism independent of Nanog and Oct4." (PMID 23326489, 2013). "Although limited by a rather low number of cases, patients harbouring SOX2 amplifications exhibited a significantly higher rate of tumor recurrences than patients lacking this event." (PMID 23544055, 2013). "Growing data demonstrates that stable expression of SOX2, OCT4 and Nanog could promote tumor cell growth, anti-apoptosis and metastasis in vitro and in vivo, therefore play an important role in carcinogenesis." (PMID 23424657, 2013). "However, Sox2 overexpressing HCT116 cells grew very poorly in these mice, indicating that Sox2-induced senescence mediated through autophagy inhibits tumor growth." (PMID 23451179, 2013). "Notch inhibition reduced Sox2, sphere and colony formation, and in vivo tumour growth exclusively in the CD44+CD24low+ population, without affecting global cell proliferation." (PMID 23982961, 2013). "SOX2 protein expression status did not correlate with age, gender, smoking status, tumor differentiation or stage." (PMID 23544055, 2013). "We evaluated the expression of the pluri potent stem cell genes Oct4, Sox2 and Klf4, as well as that of the c-Myc, Nanog and Lin28 genes in HCC samples and corresponding adjacent non-tumor liver samples obtained from 57 patients using quantitative real-time reverse transcription-PCR (qRT-PCR)." (PMID 23599755, 2013). "In contrast, ROBO1 disconnects N-cadherin from the cytoskeleton in invasive cells, thus increasing their motility; c-MYB induces expression of MGMT, resulting in higher chemoresistance; expression of SOX2 and OLIG2 result in greater stemness and higher capacity for tumour formation." (PMID 23818228, 2013). "This increase in tumor take was not due to changes in cell proliferation in vitro since there were no measurable differences in cell cycle distribution between Sox2-expressing and control LAPC-4 cells in culture (data not shown)." (PMID 23326489, 2013). "A striking observation in our study was that treatment with paclitaxel, although reducing primary tumor volume, increased significantly the number of metastatic nodules, angiogenesis (and VEGF and SDF-1 levels in tumor cells) and expression of ALDH, SOX2, CXCR4 and SDF-1 in vivo." (PMID 24278179, 2013). "To test whether Sox2 promoted a less-differentiated tumor phenotype, we measured the quantity of circulating PSA in LAPC-4-Sox2 tumor bearing animals." (PMID 23326489, 2013). "Since Sox2 is expressed in the conducting airway (including cells at the BADJs) and not SPC+ cells in the alveoli, lack of Sox2 expression in lung tumors would be consistent with a tumor origin from type II cells." (PMID 23285300, 2012). "Subsequently, in advanced mouse tumours, SOX2 expression is rarely observed, although at this stage, β-catnc clusters are not identifiable and most of the tumour cells exhibit accumulation of β-catenin in the nucleus, cytoplasm or both." (PMID 22349813, 2012). "The results showed that Sox2 and Oct4 positive staining was only seen in the nuclei of cancer cells but not in either the precancerous tissues or benign tumor tissues by immunohistochemistry (p < 0.01)." (PMID 22837720, 2012). "Together with the expression of embryonic stem cell transcription factors like Oct4, Sox2, and Nanog along with the exhibition of EMT like features and orthotopic tumor-forming ability, collectively suggest that SP cells isolated from NSCLC cell lines and tumors have stem-like properties." (PMID 23009336, 2012).
tumor (continued). "Our data showing that depletion of Sox2 affects the self-renewal properties of stem-like cells, we next examined Sox2 expression in a panel of NSCLC tumor samples obtained from stage I/II or stage IV patients on tissue microarrays (TMAs) by immunohistochemistry." (PMID 23009336, 2012). "Analysis of Sox2 expression, a GSC marker, showed that 25.9% of transplanted GSCs and their descendants were Sox2+ as compared to 0.1% of nonstem tumor cells and their descendants." (PMID 22973309, 2012). "The results indicated that expressions of SOX2 and Oct 4, but not those of Wnt-1, 2 and10a, were upregulated in SP cells isolated from D121 tumour cells when compared with those of non-SP cells." (PMID 21468047, 2011). "Our data suggested that SOX2 might down regulate BEX1 and BEX2 expression, reducing their tumor suppressor activities and thus promoting carcinogenesis." (PMID 21211035, 2011). "A similar reduction was seen in Sox2 positive non-stem tumor cells (CFP cells) from an initial population of 7.1 percent in culture to 0.1 percent in the tumor." (PMID 21961046, 2011). "Accordingly, anti-SOX2 immunity was not related to SOX2 expression levels or tumor burden in the patients' BM." (PMID 22190969, 2011). "The highly tumorigenic NCI-H226 cells lead to systematic tumor growth with no change in growth rate according to SOX2 status." (PMID 20126410, 2010). "To rule out the possibility that Sox2 was not effectively deleted in tumor cells (a potential concern in GEMMs where rare escapees may give rise to tumors), we examined whole-head sections by IHC." (PMID 41266112, 2026). "One reason for the difference in results between the immunochemical analyses could be nonspecific cytoplasmic staining in tumor cells, which may be falsely interpreted as nuclear SOX2 localization, leading to false positives in the semiautomatic analysis." (PMID 41189680, 2026). "Particularly in NSCLC, SOX proteins exhibit dual regulatory functions: Certain members (SOX2) may promote chemotherapy resistance by maintaining cancer stem cell properties, whereas others (SOX17) serve as tumor suppressors by inhibiting oncogenic signaling pathways." (PMID 41268614, 2026). "Evaluation of cancer stem cell-associated markers showed consistent expression of CD44, Nanog, Oct3/4, and Sox2 in the original tumours and cell lines, while CD133, Nestin, and Trop2 were present in the tumours but absent in vitro, indicating selective loss of specific stem-like populations." (PMID 41828941, 2026). "However, in other cancers, such as gastric and liver, RBBP4 is recruited as a part of the NURF complex to promote transcription of certain factors [e.g., SRY-Box Transcription Factor 2 (SOX2) and Octamer-Binding Transcription Factor 4 (OCT4)] that drive tumor progression." (PMID 41278204, 2025). "Additionally, A2aR overexpression induces G1 phase arrest and significantly upregulates stem cell markers such as Nanog, octamer-binding transcription factor 4 (OCT-4), and SRY-box transcription factor 2 (SOX-2), providing tumor cells with enhanced proliferative and repair capabilities." (PMID 40725100, 2025). "On the other hand, SOX2 may interact with tumor-specific non-embryonic chaperone proteins in cancer cells to regulate a novel set of genes, executing unique non-stemness biological functions." (PMID 40821114, 2025). "Therefore, identifying targetable factors upstream or downstream of SOX2 and ensuring that these factors can suppress tumor growth without adversely affecting normal tissue are important directions for future research." (PMID 40821114, 2025). "Moreover, ERCC6L knockdown resulted in decreased levels of SOX2 and OCT4 in tumor tissues." (PMID 40691138, 2025). "In addition, key stemness markers, including NANOG, OCT4 and SOX2, were markedly upregulated in DUSP9‐overexpressing tumours, whereas their expression was significantly reduced in DUSP9‐knockdown tumours, further supporting the role of DUSP9 in promoting stemness." (PMID 41383134, 2025).